ZNF630 (zinc finger protein 630)
Description:
May be involved in transcriptional regulation.
Synonyms: BC037316; dJ54B20.2; FLJ20573; MGC138344
Tractability: PROTAC: ubiquitination databases record sites on it.
Gene: Protein-coding gene on chromosome X (47,983,356 to 48,071,893, reverse strand). Ensembl gene ENSG00000221994.
Subcellular location: Nucleus
Subcellular location (Human Protein Atlas): Nucleoplasm; Cytosol
Gene Ontology:
Molecular function: DNA-binding transcription factor activity, RNA polymerase II-specific; RNA polymerase II cis-regulatory region sequence-specific DNA binding; DNA binding
Biological process: regulation of transcription by RNA polymerase II; regulation of DNA-templated transcription
Cellular component: nucleus; nuclear lumen
Homologues: Orthologues: chimpanzee ZNF630 (96% identical), dog ZNF630 (78% identical), pig ZNF630 (77% identical). Paralogues in human: ZNF300 (54% identical), ZNF41 (48% identical), ZNF182 (46% identical), ZNF484 (46% identical), ZNF605 (44% identical), ZNF658 (43% identical), ZNF782 (43% identical), ZNF33B (43% identical), ZNF585B (43% identical), ZNF717 (42% identical), ZNF175 (41% identical), ZNF568 (41% identical), and 164 more.
Diseases named in the same sentence as ZNF630 in open-access papers:
ZNF630 is named in the same sentence as 2 diseases in open-access papers, as found by Europe PMC text mining. Sharing a sentence is not in itself a finding about the gene and the disease. The quoted sentences say what the papers report.
cancer (1 paper, 2017). A tumor composed of atypical neoplastic, often pleomorphic cells that invade other tissues. "The remaining variants were located in genes of largely unknown function such as (CFAP47, ITIH6 and ZNF630) or in cancer-associated genes namely; INTS6L90, 91 and SSX392." (PMID 28720891, 2017).
ZNF630 also shares sentences with these, for which no sentence is quoted: pontocerebellar hypoplasia (1 paper).